IL2 (interleukin 2)
Diseases named in the same sentence as IL2 in open-access papers (continued):
Sharing a sentence is not in itself a finding about the gene and the disease.
colorectal adenocarcinoma (2 papers, 2015 to 2022). The most common type of colorectal carcinoma. "We then evaluated the performance of mHsp70-targeting TKD/IL-2 stimulated NK cells and CAR T cells from the same donors against the human colorectal adenocarcinoma LS174T and LoVo cell lines with a high and low mHsp70 expression." (PMID 35720311, 2022).
colorectal adenoma (2 papers, 2010 to 2015). An adenoma that arises from the colon or rectum. "Similar to our findings, lower serum concentrations of IL-2 have been reported in colorectal adenoma and cancer patients vs healthy individuals." (PMID 20924374, 2010). "The aims of this study were to examine whether serum concentrations of IL-1β, IL-2, IL-8, IL-10, IL-12p70, GMCSF, IFNγ, and TNFα were associated with flavonol intake or could predict colorectal adenoma recurrence." (PMID 20924374, 2010). "In the current study, we examined serum concentrations of eight cytokines (IL-1β, IL-2, IL-8, IL-10, IL-12p70, GMCSF, IFNγ, and TNFα) in relation to flavonol intake and colorectal adenoma recurrence and found none to be associated with flavonol intake and with colorectal adenoma recurrence." (PMID 20924374, 2010).
contact dermatitis (2 papers, 2021 to 2023). An inflammatory skin condition caused by direct contact between the skin and either an irritating substance or an allergen. "RT-PCR analyses also revealed mRNA upregulation of pro-inflammatory cytokines (IL-1β and IL-6) and some Th1 or Th2 cytokines (IFNγ, IL-4, and IL-10), but not that of IL-2, TGFβ, and IL-17, at the delayed phase of oxazolone-induced contact dermatitis, similar within the three genotypes." (PMID 36768979, 2023).
corneal disease (2 papers, 2015 to 2021). "There is substantial evidence that the Type-1 T lymphocytes (Th1) predominantly secreting interleukin 2 (IL-2) and interferon (IFN)-γ are pathogenic in the evolution of corneal disease, since the neutralization of IL-2 and IFN-γ results in the remission of HSK." (PMID 25587898, 2015). "CD4+ Type-1 T lymphocytes (Th1) predominantly secreting interleukin 2 (IL-2) and IFN-γ were shown to induce immunopathology in the course of corneal disease." (PMID 25587898, 2015). "In this study, we evaluated the cytokine profiles of IL-2, IFN-γ, ICAM-1, IL-5, IL-6, IL-8, IL-10, IL-1β, MCP-1, IL-17A, IP-10, G-CSF, and VEGF-A in the AqH of BK patients before and after DMEK and in a control group without corneal disease." (PMID 34426617, 2021).
cryoglobulinemia (2 papers, 2014 to 2015). Cryoglobulinemia is a type of vasculitis that is caused by abnormal proteins (antibodies) in the blood called 'cryoglobulins.' At cold temperatures, these proteins become solid or gel-like, which can block blood vessels and cause a variety of health problems. "In a recent audit of VASCU-IL-2 trial, errors lead to a correction and update of results that include loss of significance for both the decrease of cryoglobulinemia and the increase of C4 levels during administration of LD IL-2 in original report." (PMID 26793191, 2015). "Studies with IL-2 in humans are limited to cryoglobulinemia in which case infusion of low dose IL-2 was followed by an increase in Treg and was associated with clinical improvement." (PMID 25343479, 2014).
Cryptococcal meningitis (2 papers, 2025). Meningeal inflammation produced by cryptococcus neoformans, an encapsulated yeast that tends to infect individuals with acquired immunodeficiency syndrome and other immunocompromised states. "18-week survival after diagnosis of cryptococcal meningitis was associated with higher CSF leukocytes at baseline with greater T helper 1 (IFN-γ, IL-2 and TNF-α cytokines), T helper 17 (IL-17A cytokine) and CXCR3+ T cell (CXCL10 chemokine) responses." (PMID 39928682, 2025). "Our study suggests that mortality following cryptococcal meningitis is associated with paucity of CSF CXCR3+ T cell activating chemokine CXCL10, cellular growth activating cytokine IL-2, and immune checkpoint regulatory element PD-L1." (PMID 39928682, 2025). "With survival, after adjusting for cytokine and chemokine responses, IL-2 (p = 0.0353) and CXCL10 (p = 0.0045) independently predicted survival with cryptococcal meningitis (model 1 and S7)." (PMID 39928682, 2025). "Other variables including peripheral white blood cells, PD-L1, CXCL10, CCL11, IFN-γ, IL-2 and IL-10 did not independently predict the levels of CSF leukocytes count with cryptococcal meningitis." (PMID 39928682, 2025).
cysticercosis (2 papers, 2011 to 2013). "In early stages of experimental cysticercosis a clear but transient Th1-type immune response develops (high levels of IL-2 and IFN-γ), but as infection time progresses a permanent Th2-type response follows (high levels of IL-4, IL-6 and IL-10)." (PMID 21912714, 2011).
dental caries (2 papers, 2021 to 2025). The decay of a tooth, in which it becomes softened, discolored, and/or porous. "We suggest a further validation of the four biomarkers (IL-4, IL-13, IL-2-RA, and eotaxin/CCL11) in the context of JAK/STAT signaling and dental caries." (PMID 33806927, 2021). "The current research identified four biomarkers (IL-4, IL-13, IL-2-RA, and eotaxin/CCL11) that enabled the correct diagnosis of dental caries in 37 out of 38 patients using RF analysis." (PMID 33806927, 2021).
dilated cardiomyopathy (2 papers, 2020 to 2023). Cardiomyopathy which is characterized by dilation and contractile dysfunction of the left and right ventricles. "However, other studies have reported a worse prognosis in patients with elevated IL-2 levels and dilated cardiomyopathy." (PMID 38109427, 2023).
disseminated candidiasis (2 papers, 2021 to 2022). Systemic candidiasis occurs when Candida yeast enters the bloodstream and may spread (becoming disseminated candidiasis) to other organs, including the central nervous system, kidneys, liver, bones, muscles, joints, spleen, or eyes. "SITO demonstrated a protective immune response via the induction of Th1 against disseminated candidiasis by increasing the IL-2 and IFN-γ expressions in mice." (PMID 35745788, 2022). "Increased levels of IL-2 suggest that LMM6 contributes to the protection against disseminated candidiasis." (PMID 33800117, 2021).
Dysmenorrhea (2 papers, 2017 to 2021). Pain during menstruation that interferes with daily activities. "In addition, moxibustion could downregulate NF-κB expression and inhibit the release of TNFα and IL-2 in rats with dysmenorrhea." (PMID 34899943, 2021). "SFZYD has also been shown to effectively treat dysmenorrhea, a primary symptom of blood stasis, by regulating the expression of inflammatory cytokines, such as IL-1β, TNF-α, IL-10, IL-2 and IL-12, in a rat model." (PMID 28570676, 2017).
dysplasia (2 papers, 2015 to 2025). A usually neoplastic transformation of the cell, associated with altered architectural tissue patterns. "However, our inverse associations with dysplasia are consistent with a previous study that found that IL‐2, IL‐5, IL‐8, IL‐10, IL‐13 and TNF‐alpha tend to be downregulated in low‐grade/moderate dysplasia of the pancreas compared to serous cystadenoma without dysplasia." (PMID 39482824, 2025).
filariasis (2 papers, 2013 to 2021). "The description of an anergic molecular signature within the PBMC of filariasis patients and the findings that addition of IL-2 can restore the in vitro immune responsiveness of human PBMC, reinforce the idea that Th2 hypo-responsiveness is a form of anergy." (PMID 23516361, 2013).
foot and mouth disease (2 papers, 2011 to 2020). A viral infectious disease that results in infection in cattle and swine, has material basis in foot-and-mouth disease virus, which is transmitted by contaminated fomites, or transmitted by ingestion of food contaminated with infected meat or animal products. "(2009) showed that IFNγ, IL-10, and TNFa had peaked on week 3 in response to inactivated foot-and-mouth disease (FMD) vaccination while the remaining cytokines (IL-2, IL-4, IL-12p40) peaked on the 2nd week and decreased by the 3rd week." (PMID 33251155, 2020). "In this study, we investigated the effects of GM-CSF and IL-2 as adjuvant on the immune responses of VP1 recombinant protein as a model antigen for foot and mouth disease." (PMID 21214955, 2011).
gastric adenocarcinoma (2 papers, 2021 to 2025). "This, along with enriched neighborhood genes for IL2, interferon gamma (IFNG), and IL12, augment the argument that innate responses may play a significant role in the immune microenvironment of gastric SRCC compared to gastric adenocarcinoma." (PMID 41511314, 2025).
gastric tumor (2 papers, 2020 to 2021). "Mice (NOG, female, 6–8 weeks old) with xenograft gastric tumors were treated with PBS, ex vivo IL-2-activated NK cells, IL-2-activated NK cell along with human anti-PD-1 (Nivolumab), and IL-2-activated pretreated NK cells with anti-PD-1 antibody." (PMID 34588986, 2021).
gastrointestinal infection (2 papers, 2020 to 2024). "In the context of poultry intestinal infections, IL-2 has been shown to play a role in the activation of T cells and the development of protective immunity." (PMID 38956671, 2024).
H1N1 influenza (2 papers, 2013 to 2015). "Cells from a subset of subjects (n = 16) were also analyzed for responses to H1N1 influenza in the context of IL-2 blockade or IgG depletion." (PMID 25855356, 2015). "In summary, rLH5 vaccine induced cross-protective immune response against heterosubtypic influenza A/H1N1 virus infection in mice, and this cross-protection was improved with IL-2 as an adjuvant." (PMID 24053449, 2013).
hemorrhagic disease (2 papers, 2018 to 2025). Spontaneous or near spontaneous bleeding caused by a defect in clotting mechanisms (blood coagulation disorders) or another abnormality causing a structural flaw in the blood vessels (hemostatic disorders). "Co-expression of the IL-2 and VP60 genes in a DNA vaccine for rabbit hemorrhagic disease induced higher levels of neutralizing antibodies and IL-4 expression, while reducing tissue damage upon challenge, confirming the effectiveness of IL-2 as an adjuvant." (PMID 41194927, 2025). "Consistent with hemorrhagic disease, negative control animals showed signs of liver damage as evidenced by increased levels of liver enzyme AST, and several key cytokines such as IL-1β, IL-6, IL-1Ra, MIP-1α, TNFα, IFN-γ, IL-2, and FGF-β." (PMID 30723475, 2018).
hip fracture (2 papers, 2012 to 2022). Traumatic or pathological injury to the hip in which the continuity of either the femoral head, femoral neck, intertrochanteric or subtrochanteric regions is broken. "Unsurprisingly, our study also observed significantly increased levels the Th1 (combination of IL-2, IFN-γ and IL-12) and T cell growth and activation factors (a combination of IL-4, IL-7, IL-9, IL-12, IL-15, GM-CSF) in the delirious hip fracture patients compared to the non-delirious group." (PMID 35641947, 2022).
Huntington disease (2 papers, 2008 to 2015). Huntington disease (HD) is a rare neurodegenerative disorder of the central nervous system characterized by unwanted choreatic movements, behavioral and psychiatric disturbances and dementia.
hydronephrosis (2 papers, 2011 to 2026). Collection of urine in the renal pelvis that results in dilatation of the renal pelvis and calyces. "One treatment-related death occurred: a patient with baseline hydronephrosis tolerated chemotherapy and TIL infusion but deteriorated two days after the tenth IL-2 dose, dying of refractory metabolic acidosis with no clear anatomic cause at autopsy." (PMID 41598579, 2026).
Hypercholesterolemia (2 papers, 2018 to 2023). An increased concentration of cholesterol in the blood. "Frequency of CD4CD38HLADR+ cells was negatively correlated with levels of IL-2 (r = −0.639, p = 0.01) and IL-6 (r = −0.0561, p = 0.03) in patients with hypercholesterolemia." (PMID 29997625, 2018). "Among patients presenting with hypercholesterolemia, the frequency of CD4CD38HLDR+ cells were negatively correlated to IL-6 (r = −0.561, p = 0.03) and to IL-2 levels (r = −0.630, p = 0.01)." (PMID 29997625, 2018). "However, Il-2 and IL-6 were negatively correlated with activated CD4+ T cells in patients presenting with hypercholesterolemia." (PMID 29997625, 2018). "However, levels of IL-2 and IL-6 were negatively correlated with activated CD4+ T cells in patients with hypercholesterolemia." (PMID 29997625, 2018).
Hypocalcemia (2 papers, 2013 to 2022). An abnormally decreased calcium concentration in the blood. "The results of Th1/Th2 cytokines in peripheral blood showed that the levels of serum IL-2, IL-10, IL-6 and IFN-γ in SLE patients with hypocalcemia were significantly increased." (PMID 35757710, 2022).
idiopathic pulmonary fibrosis (2 papers, 2021). Idiopathic pulmonary fibrosis (IPF) is a nonneoplastic pulmonary disease that is characterized by the formation of scar tissue within the lungs in the absence of any known cause. "S100A8 and S100A9 are upregulated in the acute exacerbations of idiopathic pulmonary fibrosis (IPF) suggesting roles of different signaling pathways like Clathrin-mediated endocytosis signaling, atherosclerosis signaling, and IL2 signaling in the pathogenesis of acute exacerbations of IPF." (PMID 34239729, 2021).
imbalance (2 papers, 2018 to 2023). "The finding of increased IL-2 levels relating to lower levels of negative symptoms suggests that immune imbalances relate to a wide spectrum of symptomatology." (PMID 29803226, 2018).
infantile epileptic spasms syndrome (2 papers, 2019 to 2025). "A study on 23 Chinese subjects with West syndrome described the presence of increased levels of serum interleukin-2 (IL-2), TNF-α, and Interferon-alpha (IFN-α) compared to matched controls." (PMID 31156384, 2019).
infectious encephalitis (2 papers, 2022 to 2025). An acute infectious process that affects the brain tissue. "A non-human primate model of ICANS demonstrated an elevation of CSF cytokines, such as IL-6, IL-2, GM-CSF, and vascular endothelial growth factor (VEGF), together with CAR-T and non-CAR-T-cell accumulation in the CSF and brain parenchyma, similar to that seen in non-infectious encephalitis." (PMID 40332772, 2025). "In addition, subgroup analysis demonstrated non-significant increase in the concentration of IL-2 in infectious encephalitis (SMD = 0.87; 95% CI, -0.89–2.63; P = 0.33) with high heterogeneity (Q = 11.57; P < 0.01; I2 = 91%)." (PMID 36048783, 2022).
ischemic colitis (2 papers, 2012 to 2023). Inflammation of the colon due to colonic ischemia resulting from alterations in systemic circulation or local vasculature. "With immunosuppressive treatment, there are reported few cases of ischemic colitis, induced by immunomodulators like interleukin-2 (IL-2) or interferon (IFN), sodium aurothiomalate, and steroid therapy also associated with azathioprine." (PMID 23346428, 2012).
Kawasaki disease (2 papers, 2023). A rare inflammatory disease characterized by an acute febrile, systemic, self-limiting, medium-vessel vasculitis primarily affecting children. "IL-1β has previously been reported to play a key role in the inflammatory profile of Kawasaki disease, and IL-2 is significantly higher in children with Kawasaki than in healthy controls." (PMID 37064248, 2023). "In Kawasaki disease, there is evidence of imbalanced Th1/Th2 cell responses, and the plasma level and mRNA expression levels of Th1 cytokines (IFN-γ, IL-2) and Th2 cytokines (IL-4 and IL-10) are markedly elevated during the acute stage of Kawasaki disease." (PMID 37841239, 2023).
keratoconus (2 papers, 2022 to 2025). A degenerative, structural disorder of the eye, characterized by a cone-shaped protrusion of the cornea. "The stable keratoconus group exhibited significantly elevated levels of tear fluid inflammatory cytokines compared to controls (all P < 0.05, except IL-2)." (PMID 40980981, 2025).
kidney transplant (2 papers, 2014 to 2019). A surgical procedure in which one or both kidneys from a donor are implanted into a recipient. "In terms of the impact of IL2 -330T > G, IL10 -1082G > A, and TNF -308G > A on BPAR incidence, our results are in accordance with previous meta-analyses indicating these SNPs are not significant determinants of BPAR incidence in Caucasian kidney transplant recipients receiving TAC or ciclosporin." (PMID 32153387, 2019).
large granular lymphocytic leukemia (2 papers, 2017 to 2020). "IL2 and IL15 activate lymphoproliferative signaling through JAK1/JAK3-STAT3/STAT5 and IL15 has shown to be elevated in large granular lymphocytic leukemia." (PMID 29228628, 2017).
Lassa fever (2 papers, 2021 to 2024). A viral hemorrhagic fever that is caused by the Lassa virus, which is transmitted by contact with infected rodents; it is characterized by fever, headache, malaise, myalgia, and hearing loss. "The IFNα and γ response, E2F target, IL6/JAK/STAT3, G2/M checkpoint, IL2/STAT5 and complement pathways were activated during Lassa fever, as shown by comparison with mock-infected animals, but this activation was more intense after Josiah LASV infection." (PMID 39652618, 2024). "Evaluations of VSV-vectored and MV-vectored Lassa fever vaccines have similarly observed an IFN-γ- and TNF-α-driven effector response post vaccination; IL-2 expression in response to antigen re-exposure was not assessed in these studies." (PMID 33654106, 2021).
lentivirus infection (2 papers, 2013 to 2018). Virus diseases caused by the Lentivirus genus. "The reduction in Foxp3 binding at the IL-2 promoter may translate into restoring or enhancing IL-2 function in the dysfunctional CD8+ T cells during lentivirus infections." (PMID 29861472, 2018). "Freshly isolated human peripheral blood lymphocytes (PBL) from healthy HLA-A2 donors were stimulated for 48 hours with anti-CD3/CD28 microbeads and human IL-2 then exposed to a single round of lentivirus infection or nucleofected with transposon/transposase DNA plasmids." (PMID 23840834, 2013).
Lewis lung carcinoma (2 papers, 1997 to 2003). "Mice grafted with the 3LL (Lewis lung) carcinoma exhibit immune suppression: spleen cells showed decreased spontaneous interleukin 2 (IL-2) production and T-CD4+ and T-CD8+ lymphocyte populations; in addition the polyamine content in the spleen was increased." (PMID 9252204, 1997). "Furthermore, a synergistic combination between IL-2 and IL-12 was observed in a Lewis lung carcinoma model where only vaccination with dual-gene transduced cells inhibited growth of established tumours." (PMID 12771934, 2003).